MAP9 (microtubule associated protein 9)
Description:
Involved in organization of the bipolar mitotic spindle. Required for bipolar spindle assembly, mitosis progression and cytokinesis. May act by stabilizing interphase microtubules.
Synonyms: ASAP; FLJ21159
Tractability: PROTAC: its protein half-life has been measured.
Gene: Protein-coding gene on chromosome 4 (155,342,658 to 155,376,970, reverse strand). Ensembl gene ENSG00000164114.
Subcellular location: Cytoplasm; Cytoplasm, cytoskeleton; Cytoplasm, cytoskeleton, spindle
Subcellular location (Human Protein Atlas): Primary cilium; Primary cilium transition zone; Centrosome; Nuclear speckles
Gene Ontology:
Molecular function: microtubule binding
Biological process: mitotic spindle assembly; regulation of mitotic centrosome separation; regulation of mitotic cytokinesis; regulation of mitotic spindle organization; mitotic cytokinesis; spindle assembly
Cellular component: astral microtubule; cytoplasm; mitotic spindle; spindle midzone; axon; aster; cytoskeleton; microtubule cytoskeleton; mitotic spindle midzone; spindle
Genetic constraint (gnomAD): Loss-of-function variants: 33 observed, 32.47 expected, observed/expected ratio (o/e) 1.02, 90% interval 0.77 to 1.36. The upper end of that interval is the gene's LOEUF score, 1.36, which puts it in group 5 of 6, group 1 being the genes least tolerant of losing a copy. Missense variants: 420 observed, 420.52 expected, observed/expected ratio (o/e) 1, 90% interval 0.92 to 1.08. Synonymous variants: 141 observed, 145.2 expected, observed/expected ratio (o/e) 0.97, 90% interval 0.85 to 1.12.
Homologues: Orthologues: chimpanzee MAP9 (99% identical), macaque MAP9 (96% identical), dog MAP9 (83% identical), rabbit MAP9 (80% identical), pig MAP9 (77% identical), guinea pig MAP9 (71% identical), rat Map9 (70% identical), mouse Map9 (70% identical), tropical clawed frog map9 (34% identical), zebrafish map9 (26% identical), Caenorhabditis elegans maph-9 (17% identical).
Diseases named in the same sentence as MAP9 in open-access papers:
MAP9 is named in the same sentence as 21 diseases in open-access papers, as found by Europe PMC text mining. Sharing a sentence is not in itself a finding about the gene and the disease. The quoted sentences say what the papers report.
colorectal cancer (3 papers, 2014 to 2023). A primary or metastatic malignant neoplasm that affects the colon or rectum. "The expression of the microtubule-associated protein MAP9 is altered in both colorectal cancer and breast cancer, leading to cell cycle dysregulation." (PMID 36901727, 2023). "Actually, previous studies did uncover that MAP9 is associated with the progression of gastric cancer, colorectal cancer, and HCC." (PMID 35656338, 2022). "In colorectal cancer, the MAP9 expression was frequently silenced, and MAP9 loss initiated tumorigenesis and was associated with poor survival of patients." (PMID 35656338, 2022). "In fact, the dysregulation or hypermethylation of MAP9 has been detected in certain types of tumors, such as hepatocellular carcinoma (HCC) and colorectal cancer." (PMID 35656338, 2022).
cone-rod dystrophy (3 papers, 2017 to 2024). Inherited retinal dystrophies that belong to the group of pigmentary retinopathies. "A homozygous variant in the MAP9 gene has been reported to accelerate disease progression in a naturally-occurring canine RPGRIP1-associated cone-rod dystrophy." (PMID 38979372, 2024). "Hence, we characterized the pathogenic phenotypes associated with homozygous MAP9 variant, and investigated the molecular function of MAP9 in primary cilia using the RPGRIP1-associated oligogenic canine cone-rod dystrophy model as well as cultured cells." (PMID 37650070, 2023). "In a canine cone-rod dystrophy model, a naturally occurring 44-bp exonic insertion in RPGRIP1 (RPGRIP1ins44/ins44) is the primary disease locus while an additional homozygous variant in MAP9 (microtubule associated protein 9) (MAP9aff/aff) acts as a modifier associated with early disease onset." (PMID 37650070, 2023).
breast carcinoma (2 papers, 2014 to 2023). "High expression of MAP9 is positively correlated with relapse-free survival in breast cancer patients (p = 0.0023)." (PMID 36901727, 2023). "MAP9 hypermethylation in breast cancer leads to decreased expression and may have utility as an epigenetic biomarker." (PMID 36901727, 2023). "In this CGH analysis the authors show that, indeed, in breast cancer, there is amplification of the 20q and 16p regions (AURKA and PLK1) whereas the 4q region is often deleted, indicating that downregulation of MAP9 (4q32.1) could be the result, at least in part, of a gene loss." (PMID 24876664, 2014). "In ductal breast cancer, we found a grade-dependent increase of AURKA expression (P > 10−3), while the variations of expression of MAP9 and PLK1 are not significant (P > 0.2)." (PMID 24876664, 2014).
gastric cancer (2 papers, 2021 to 2022). A primary or metastatic malignant neoplasm involving the stomach. "Increasing reports have identified various downstream genes of miR-320a including programmed cell death protein 1 (PD1) in malignant mesothelioma, interleukin 4 in preeclampsia, microtubule-associated protein 9 (MAP9) in postmenopausal osteoporosis, and Rab protein 14 (RAB14) in gastric cancer." (PMID 34720057, 2021).
asthma (1 paper, 2024). "There are multiple observations that connect MAP9 to cancer progression and hypertension, but reliable information in unavailable regarding MAP9 polymorphism and asthma." (PMID 39406500, 2024).
bladder cancer (1 paper, 2022). "Our study provides a comprehensive analysis of MAP9 and revealed MAP9 as a potential target for gene therapy of human bladder cancer." (PMID 35656338, 2022). "MAP9 is responsible for bipolar spindle assembly and is involved in the progression of many types of tumors; however, its role in bladder cancer (BC) remains unknown." (PMID 35656338, 2022).
breast tumors (1 paper, 2014). "In summary, genomic instability, that is, gene gains and losses, correlates with up- and downregulation of MAP9 and its two partners and could be a characteristic of colorectal and breast tumors." (PMID 24876664, 2014). "In the present study, we analyzed 26 colorectal tumors versus adjacent coupled normal tissues from the same patients as well as 77 ductal breast tumors to determine whether the deregulation of MAP9 expression could be correlated with malignancy and therefore could be of prognostic value." (PMID 24876664, 2014). "In this study we have analyzed the expression of MAP9/ASAP and its two partners AURKA and PLK1 in colorectal and breast tumors." (PMID 24876664, 2014).
colorectal tumors (1 paper, 2014). "For example high level gain was observed at 20q where AURKA is located, frequent gain at 16p (PLK1), and loss at 4q (MAP9) in a number of colorectal tumors." (PMID 24876664, 2014). "In parallel, GEO data set analyses (GDS 2947) of colorectal tumors and adjacent normal tissue show downregulation of MAP9 and upregulation of AURKA and PLK1, with values that are similar to what we observed in this study." (PMID 24876664, 2014). "We show here that, in colorectal tumors, MAP9 is strongly underexpressed whereas AURKA and PLK1 are overexpressed." (PMID 24876664, 2014). "We show here that, in contrast to the two kinases, MAP9 is downregulated in colorectal tumors." (PMID 24876664, 2014).
retinal tumor (1 paper, 2023). "To validate the localization of MAP9 and RPGRIP1 in primary cilia, we performed ICC with a cell culture model using mouse-derived immortalized retinal tumor cell line, 661W." (PMID 37650070, 2023).
tumor (3 papers, 2014 to 2023). "Further, the loss of MAP9 caused decreased BC cell proliferation via inducing the growth 1/synthesis (G1/S) cell cycle arrest in vitro and slowed tumor growth in vivo." (PMID 35656338, 2022). "Immunohistochemistry detected a significant lower MAP9 expression in tumor tissues in the sh-MAP9 group compared to the sh-ctrl group." (PMID 35656338, 2022). "MAP9 expression increased in the tumor tissues, and its increased level was negatively correlated with prognosis." (PMID 35656338, 2022). "We found that knocking down MAP9 attenuated cell proliferation via inducing the G1/S cell cycle arrest and inhibited tumor growth." (PMID 35656338, 2022). "We found that MAP9 expression was positively related to the tumor size and negatively related to the overall survival rates of patients." (PMID 35656338, 2022). "MAP9 has a significant influence on tumor immune microenvironment and could be a potential biomarker for immunotherapy." (PMID 35656338, 2022). "Considering the interactions of MAP9 with Plk1 and AURKA, we hypothesized that MAP9 is vital in tumor progression." (PMID 35656338, 2022). "However, the role of MAP9 in tumor immunity is remains unknown." (PMID 35656338, 2022). "Our study revealed that AURKA is a bona fide marker of the severity of the disease whereas PLK1 and MAP9 expression does not correlate with the tumor grade." (PMID 24876664, 2014). "To determine whether MAP9 could promote tumor growth, we compared the proliferative abilities of BC cell lines and tumor size in nude mice with or without MAP9 silencing." (PMID 35656338, 2022). "The MAP9 gene showed a significantly consistent expression pattern in the cohorts, but its high expression could not be determined to contribute to tumorigenesis as the tumor tissues in the TCGA cohort had a lower expression than the normal tissues." (PMID 36748835, 2023).
cancer (2 papers, 2014 to 2024). A tumor composed of atypical neoplastic, often pleomorphic cells that invade other tissues. "It is possible that the perturbation of MAP9 homeostasy may participate in the phenotype of cancer cells and that its expression in these cells is still sufficient to allow mitosis to proceed, or that other pathways may overcome MAP9 deficiency." (PMID 24876664, 2014).
colorectal (1 paper, 2014). "MAP9 downregulation is associated with colorectal malignancy and could be used as a disease marker and a new drug target, while AURKA and PLK1 are upregulated." (PMID 24876664, 2014). "Despite the fact that the use of microtubule disruptors might overcome secondary effects on normal cells, MAP9 might be considered as a potential new target for anticancer therapies and a marker of colorectal malignancy." (PMID 24876664, 2014).
neurological disorders (1 paper, 2021). "They include characteristic genes, Prnp, Cct4, Vegfd (Figf), Map9 (Mtap9), Pik3cg, Zfand5, Endog, and Hbq1, which are reportedly associated with AD, CJD, and/or related neurological disorders." (PMID 34959983, 2021).
MAP9 also shares sentences with these, for which no sentence is quoted: retinal degeneration (2 papers); ciliopathy (1); hepatocellular carcinoma (1); Hypertension (1); malignant mesothelioma (1); oculocerebrorenal syndrome of Lowe (1); postmenopausal osteoporosis (1); preeclampsia (1).